TLR9 (toll like receptor 9)
Diseases named in the same sentence as TLR9 in open-access papers (continued):
Sharing a sentence is not in itself a finding about the gene and the disease.
autoimmune disease (102 papers, 2008 to 2025). A disorder resulting from loss of function or tissue destruction of an organ or multiple organs, arising from humoral or cellular immune responses of the individual to their own tissue constituents. "In this context, it is puzzling that many B cells activated via TLR9 during infections and autoimmune diseases differentiate into PCs, leading to effective or pathogenic humoral immune responses." (PMID 38659975, 2024). "Toll-like receptor 9 (TLR9) plays a role in autoimmune diseases, and B cell-specific TLR9 deficiency delays T1D development." (PMID 38903498, 2024). "Targeting immune responses mediated by TLR9 is a potential therapeutic strategy for preventing disease-associated inflammation and autoimmune diseases." (PMID 37605653, 2023). "It has been reported that polymorphisms in the TLR9 gene are related to an increased risk of developing other autoimmune diseases, including SLE, RA and GD." (PMID 37139337, 2023). "The TLR9 rs352140 polymorphism was reported to be associated with susceptibility to other autoimmune diseases, including SLE and GD, in the Chinese population." (PMID 37139337, 2023). "Activation of TLR7 and TLR9 by recognition of self-nucleic acids is implicated in the pathogenesis and development of autoimmune disease." (PMID 37606045, 2023). "Activation of the TLR9 signaling has been implicated in the pathogenesis of several autoimmune diseases including SSc." (PMID 33953718, 2021). "Amyloid-DNA composites are known to intensively stimulate TLR2 and TLR9, inducing immunogenic reactions, and they have been associated with the triggering of other autoimmune disorders, including systemic lupus erythematosus." (PMID 31273267, 2019). "Many studies focused on the association between TLR-9 promoter polymorphism (rs187084) and autoimmune diseases, such as SLE, rheumatoid arthritis, and OA." (PMID 28916728, 2017). "Although TLR9 gene polymorphisms have been studied in other diseases, including infectious and autoimmune diseases and some cancers, very little is known about TLR9 gene polymorphism in breast cancer." (PMID 25101078, 2014). "Although the TLR9 agonist CpG seemed quitepromising, being a strong Th1 adjuvant, clinical studies showed that vaccinescontaining CpG cause a severe autoimmune disease, Wegener’s granulomatosis." (PMID 23861971, 2013). "We next investigated if BTK was required for the TLR9 and BCR synergy as the inhibitor is of interest in SLE therapy and TLR9 is linked to the progression of this autoimmune disease." (PMID 23967355, 2013). "In this study, we investigated the effect of TLR-4 and TLR-9 gene polymorphisms on the organ-specific autoimmune disease GD in a Taiwanese population." (PMID 21050493, 2010). "Endosomal Toll-like receptors (TLRs, including TLR3, TLR7, TLR8 and TLR9) play crucial roles in immune responses by recognizing pathogen-associated molecular patterns; however, their aberrant activation is implicated in inflammatory and autoimmune diseases." (PMID 40887497, 2025). "Additional avenues of research on EGA should include its utilization as a broad-spectrum agent against viral and bacterial infection, as pointed out in its initial discovery, as well as assessment of its potential in autoimmune disease states where TLR9 is implicated in the disease pathogenesis." (PMID 37020542, 2023). "The relationship between TLR9 gene polymorphisms and autoimmune diseases has been reported." (PMID 37139337, 2023). "In addition, previous studies demonstrated that TLR9 recognizes DNA fragments released from host cells, accelerating sterile inflammation, which is associated with inflammatory diseases such as autoimmune diseases." (PMID 32714475, 2020). "TLR-9 could recognize unmethylated CpG-rich and pathogen-derived DNA sequences and increase the risk of autoimmune disease by stimulating B cells." (PMID 28916728, 2017).
autoimmune disease (continued). "TLR-9 may play pathway-dependent roles, which might partly explain the association between TLR-9 rs187084 polymorphism and some autoimmune diseases." (PMID 28916728, 2017). "Thus, TLR7 and TLR9 have opposing pathogenic and protective roles, respectively, in autoimmune disease." (PMID 28751890, 2017). "It is thus hypothesised that in some autoimmune diseases deficiency of either TLR8 or TLR9 will result in decreased competition of these endosomal TLRs to bind to Unc93B1, making TLR7 more available and resulting in higher TLR7 trafficking and response." (PMID 28553556, 2017). "TLR9 are associated with various diseases such as autoimmune diseases and infectious diseases." (PMID 24696007, 2014). "Because DNA-PKcs is an auto-antigen and regulates the immune response to CpG-ODN, it is very possible that DNA-PKcs works together with TLR9 or has an independent function in response to DNA/auto-antigen/antibody complexes during the pathogenic process of autoimmune disorders." (PMID 23533581, 2013). "Moreover, since EBV infection is correlated with the development of multiple autoimmune diseases, it might be useful to examine the effect of TLR9 inhibition on the progression and severity of other autoimmune diseases associated with EBV infection." (PMID 38731877, 2024). "Recently, TLR-7 and TLR-9 have contributed to the development of autoimmune diseases such as rheumatoid arthritis, SLE, and psoriasis." (PMID 40651955, 2025). "Taken together, lysosomal DNA stress can promote autoinflammatory and autoimmune diseases via TLR9, cGAS-STING and AIM2 activation." (PMID 40037613, 2025). "TLRs, such as TLR2, TLR4, TLR7, and TLR9, are involved in this process, and their dysfunction or overexpression in immune cells plays a pivotal role in the pathogenesis of autoimmune diseases." (PMID 38732254, 2024). "Recent advancements include the discovery of small-molecular antagonists, such as 7f, which exhibits strong on-target potency and selectivity against TLR7 and TLR9, demonstrating efficacy in the preclinical models of autoimmune diseases by oral administration." (PMID 38732254, 2024). "In mouse models of autoimmune disease, the acceleration of disease progression is not only attributable to TLR9 but also involves IFNα." (PMID 38659975, 2024). "TLR9 in Mitochondrial Innate Immunity, activated in several autoimmune diseases, including psoriasis, is currently under investigation as a potential therapeutic target, where TLR antagonists are being developed for the treatment of these conditions." (PMID 38612783, 2024). "TLR2, TLR4, TLR7, and TLR9 recognize PAMPs from infectious agents and DAMPs from tissue damage, contributing uniquely to the pathogenesis of specific autoimmune diseases." (PMID 38732254, 2024). "This is demonstrated by the fact that knocking out either Tlr8 or Tlr9 in healthy C57BL/6 mice induced SLE-like autoimmune disease, while additional knockout of Tlr7 eliminated disease symptoms, indicating that the disease development was dependent on TLR7." (PMID 38791389, 2024). "Our study outlines a posttranslational modification mechanism that regulates the TLR9 response and suggests a potential immunotherapeutic target for treating autoimmune diseases." (PMID 38169466, 2024). "Numerous studies have suggested the significant role of TLR9 in the pathogenesis of autoimmune diseases, including T1D." (PMID 37139337, 2023). "Innate immune DNA-sensing pathways, such as cGAS-STING, TLR9, and inflammasome, are well characterized as key regulators of antiviral host immune defense and autoimmune diseases." (PMID 37777633, 2023). "TLR9 is a crucial factor in controlling autoimmune diseases, and active research on TLR9 agonists and antagonists to improve autoimmune inflammation is ongoing." (PMID 38001481, 2023). "SLE is an autoimmune disease characterized by a type 1 IFN signature with a possible role for aberrant TLR9 activation in pathogenesis." (PMID 37020542, 2023).
autoimmune disease (continued). "In summary, pDCs are important players in the mechanisms underlying several autoimmune diseases and demonstrate enriched inflammatory responses through the activation of TLR7/8 and TLR9 signaling pathways and the IFN system." (PMID 36359340, 2022). "Huang and Yang confirmed the role of the TLR9/MyD88 pathway in the regulation of adaptive immune responses in autoimmune diseases." (PMID 36405992, 2022). "In particular, inappropriate signaling by TLR4, TLR7, and TLR9 induces hyper-activation of the immune system and contributes to numerous pathological conditions like inflammation and autoimmune diseases." (PMID 34025679, 2021). "Numerous studies suggest that TLR4-, TLR7- and TLR9-mediated abnormal activation of the macrophages, DCs and B cells contributes to the pathogenesis of inflammation and autoimmune diseases." (PMID 34025679, 2021). "TLR-9 is also an important factor in autoimmune diseases, and there is active research into synthetic TLR9 agonists and antagonists that help regulate autoimmune inflammation." (PMID 33773522, 2021). "The release of NET results in the emission of alarmins and formation of RNA/DNA complexes serving as costimulatory elements for TLR7/8 and TLR9, thus linking neutrophils to DCs through inducing DC maturation and the promotion of autoimmune diseases." (PMID 32473089, 2020). "Overall, these results highlight the unclear role of granulin in both the TLR9 pathway and autoimmune diseases." (PMID 30900780, 2019). "Toll-like receptor 9 (TLR9) is also known as a factor of autoimmune diseases, because TLR9 recognizes self-derived DNA and induces sterile inflammation." (PMID 29997629, 2018). "For example, IRS 954 (a TLR7/TLR9 inhibitor) has been reported to have a potential in reducing pathogenesis of autoantibody production and autoimmune tissue injury in SLE, another autoimmune disease associated with EBV." (PMID 29995930, 2018). "TLR9-mediated innate immunity and inflammation plays important roles in infectious diseases, autoimmune diseases and cancer." (PMID 30349079, 2018). "sODNs augment TLR9 activation by mammalian genomic DNA indicating the role of short DNA degradation products in the endosomes in response to infection or in autoimmune disease, particularly at limiting concentrations of ODNs." (PMID 28530246, 2017). "Stimulation through MYD88, TLR7, or TLR9 promotes autoimmune diseases, presumably by binding to RNA (TLR7), or DNA (TLR9) released from apoptotic cells." (PMID 29312329, 2017). "Although TLR9 is another promising target of therapeutic intervention in autoimmune diseases, previously established anti-TLR9 mAbs fail to inhibit TLR9 responses." (PMID 28266597, 2017). "Stimulation of TLR9 can induce an NF-κB-mediated inflammatory response that has a critical role in autoimmune disease and cancers." (PMID 28574818, 2017). "The association between Syk and TRAF6 suggests an important point of crosstalk in the context of autoimmune disease, suggesting a potential mechanism for how Syk blockade attenuates the TLR9 responses." (PMID 28751890, 2017). "One of the putative functional polymorphism is TLR9 rs5743836 polymorphism (−1237T/C polymorphism), which is located within the promoter region of TLR9 gene and has been studied in several diseases including cardiovascular, cancers and autoimmune diseases." (PMID 28321710, 2017). "Robust activation of B cells via BCR, CD40 or TLR9 is involved in the pathogenesis of autoimmune diseases." (PMID 26980135, 2016). "There are evidences in mice and human that TLR9 activation costimulates autoreactive B cells, allows breaking the tolerance and contributes to the pathogenesis of autoimmune diseases." (PMID 24801688, 2014). "In particular, IFN-α produced by pDCs upon recognition of foreign nucleic acids via TLR7 and TLR9 contributes to tolerance breakdown in several autoimmune diseases, such as SLE, SS, and psoriasis." (PMID 22826711, 2012).
autoimmune disease (continued). "The compound is specifically designed to suppress the key cytokines by inhibiting TLR7 and TLR9 activity; however, some autoimmune disease treatments specifically target inhibition of individual cytokines." (PMID 23151919, 2012). "Among the intracellular TLRs, TLR7 and TLR9 play a crucial role in the activation of autoreactive B cells, and subsequent development of autoimmune diseases such as SLE." (PMID 23151919, 2012). "We expect our findings to not only help further the understanding of TLR9 interactions in vivo but also to provide new insights towards the design and characterization of TLR9-based therapeutics for the treatment of autoimmune diseases or cancer." (PMID 21483736, 2011). "Toll-like receptor 9 (TLR9) responds to bacterial and viral DNA containing unmethylated CpG motifs and triggers immune responses in B cells; however, abnormal recognition of self-DNA by TLR9 can cause autoimmune diseases." (PMID 38659975, 2024). "Interestingly, TLR9 has been shown to be prominent in autoimmune diseases; thus our view is that injury related to ETT is an iatrogenic induced autoimmune reaction." (PMID 30548974, 2019). "In addition, we investigated the expression levels of TLR7 and TLR9 protein as these TLRs are most relevant in the context of autoimmune disease." (PMID 30761150, 2019). "Recently, in healthy individuals, serum testosterone levels was found to negatively correlate with the expression of TLR9 suggesting that this effect may have a protective role against autoimmune disease development." (PMID 31083432, 2019). "Aside from the aberrant sensing of self‐DNA by TLR9, autoimmune diseases may also result from the misregulation of intracellular TLR9 trafficking." (PMID 30900780, 2019). "This may indicate a possible utility for TLR9 inhibitors as therapeutic agents in subjects with an autoimmune disease, such as RA." (PMID 29995930, 2018). "The present study extends our understanding of TIRAP’s membrane association, which could be helpful in designing peptide decoys to block TLR2-, TLR4-, TLR7-, and TLR9-mediated autoimmune diseases." (PMID 29434596, 2018). "The PBD carries a significant segment, the PBM, that could serve as a decoy to prevent or dissociate TIRAP from the membrane in order to control dysregulated and overexpressed TLR2/TLR4/TLR7/TLR9-dependent autoimmune diseases." (PMID 29434596, 2018). "Furthermore, synergisms of BCR and TLR9 have also been reported in the development of human autoimmune diseases." (PMID 28739603, 2017). "Here we report the effects of TLR9 deficiency on autoimmune disease independent of the lpr mutation in Fas by characterizing Tlr9-/- and Tlr9+/+ mice on the Fas-intact MRL/+ genetic background." (PMID 28278279, 2017). "However, the dysregulation of TLR7, TLR8, and TLR9 plays a major role in numerous autoimmune diseases." (PMID 28553556, 2017). "Additionally, in autoimmune diseases, such as rheumatoid arthritis and systemic lupus erythematosus, self-DNA/RNA-protein complexes also activate TLR9." (PMID 26907260, 2016). "TLR9 plays a crucial role in infectious diseases, autoimmune disorders and cancers." (PMID 26907260, 2016). "TLR9 locates in endosomes and is responsible for sensing unmethylated CpG-DNA, discriminates between self- and foreign DNA, and plays an important role in many immune diseases such as autoimmune diseases and cancer." (PMID 24696007, 2014). "In principle, the signals sent by TLR7 and TLR9 should be very similar, so why are some autoimmune diseases associated with TLR7 but not TLR9?" (PMID 23426937, 2013). "TLR7- and TLR9-mediated cytokines are critical factors in autoimmune disease." (PMID 23151919, 2012). "Intracellular TLRs, particularly TLR7 and TLR9, are involved in various autoimmune diseases by sensing immune complexes such as small ribonucleotide proteins comprised of self-nucleotides; an association between inflammation and cancer development has long been appreciated." (PMID 23151919, 2012).
autoimmune disease (continued). "To conclude, the AC stimulation of TLR9 resembles the inflammatory milieu in SS autoimmune disease as in many other autoimmune diseases, and the enhanced inflammatory cytokine and costimulatory response in SSS BMDMs may contribute to the initiation of an autoimmune environment." (PMID 36359340, 2022). "High levels of TLR2 and TLR4 expression on myeloid DCs and TLRs TLR7 and TLR9 present in pDCs may have specific functions in autoimmune disease in which molecular mimicry or autoantibodies to essential nucleic acids are a potential underlying mechanism for autoimmune disease onset." (PMID 28396662, 2017). "Therefore, targeting TLR9 and modulating TLR9 signaling using Hs90 inhibitors or siRNA to Hsp90 have emerged as important strategies for the treatment of self-nucleic acid-related autoimmune diseases, including SLE." (PMID 27252703, 2016). "BTK is required for synergistic cytokine response by TLR9 and BCR in human and murine B cells, with implications in B cell activation and autoimmune diseases." (PMID 40980882, 2025). "In autoimmune disorders, NET-derived DNA complexes activate pDCs via TLR9, amplifying IFN-α-driven inflammation in SLE and other rheumatic diseases." (PMID 40442839, 2025). "Since PKM2 positively regulates the activation of the TLR4/TLR7/TLR9 pathways under in vitro conditions, the effect of PKM2 in relieving the TLR-mediated inflammation and autoimmune diseases was assessed." (PMID 34025679, 2021). "TLR-8 specifically plays a role in autoimmune disorders because it is involved in the regulation of TLR-7 and TLR-9 signaling and a direct link has been found between the dysregulation of TLR-8 activation and pathological inflammation." (PMID 32477333, 2020). "Some AMPs are also strongly immunomodulatory: LL37-DNA complexes potently amplify Toll-like receptor 9 (TLR9) activation in immune cells and exacerbate autoimmune diseases." (PMID 30833557, 2019). "Autoimmune disease in MRL-lpr mice is dependent on TLR7, TLR9, and toll-like receptor (TLR) signal transduction molecule Myeloid differentiation primary response 88 (MYD88)." (PMID 31824490, 2019). "In autoimmune disease, synergistic BCR–TLR7/TLR9 activation by NA-IC results in increased B cell proliferation and autoantibody production." (PMID 28751890, 2017). "Previous clues that TLR7 and TLR9 are handled differently by UNC93B1 came from experiments which showed that mice harbouring a mutant form of UNC93B1 succumbed to severe autoimmune disease due to enhanced TLR7 signalling and impaired TLR9 responses." (PMID 23426937, 2013). "CpG 52364 is a small molecule TLR antagonist specifically developed for TLR7, TLR8, and TLR9 to inhibit progression of SLE and other autoimmune diseases at an early stage by blocking inappropriate TLR activation." (PMID 23151919, 2012). "A plethora of studies have connected TLR9 with non-microbial diseases, e.g., hepatitis and autoimmune diseases (21, –, 23)." (PMID 40980882, 2025). "Despite being homologous proteins both expressed in B cells, studies in mice have showed that TLR7 and TLR9 manifest distinct regulation and have opposing roles in mouse models of autoimmune disease, with TLR7 promoting while TLR9 negatively regulating disease pathogenesis." (PMID 40904452, 2025). "Heightened TLR7/8, TLR9, and IFN-α signaling pathways in immune cells from Black individuals support distinct immune phenotypes observed in response to infection, vaccines, and autoimmune disease." (PMID 37606045, 2023). "Given that TLR7, TLR9, and type I IFN are key drivers of murine autoimmune disease, we investigated whether differences in TLR and IFN signaling pathways may underlie the observed ancestry-based differences in immune phenotypes in health and SLE disease." (PMID 37606045, 2023). "TLR9 induces NF-κB via the MyD88-dependent pathway, where CD82 acts as an important regulator of TLR9-mediated signaling in cancer, infectious diseases, and autoimmune diseases." (PMID 37113698, 2023).